RNU1-139P (RNA, U1 small nuclear 139, pseudogene)
Gene: Small nuclear RNA gene on chromosome 21 (19,345,148 to 19,345,312, forward strand). Ensembl gene ENSG00000212609.
Homologues: Orthologues: chimpanzee U1 (96% identical), guinea pig U1 (70% identical), rat LOC120093368 (62% identical), mouse Gm55339 (48% identical). Paralogues in human: RNU1-89P (85% identical), RNU1-1 (84% identical), RNU1-2 (84% identical), RNU1-27P (84% identical), RNU1-28P (84% identical), RNU1-3 (84% identical), RNU1-4 (84% identical), RNVU1-18 (84% identical), RNVU1-29 (84% identical), U1 (84% identical), RNVU1-28 (84% identical), RNVU1-31 (84% identical), and 134 more.